Y_RNA (Y RNA )
Gene: Miscellaneous RNA gene on chromosome 19 (11,408,772 to 11,408,880, forward strand). Ensembl gene ENSG00000202357.
Homologues: Orthologues: chimpanzee Y_RNA (100% identical), macaque Y_RNA (92% identical). Paralogues in human: RNY1 (96% identical), Y_RNA (92% identical), Y_RNA (91% identical), RNY1P11 (90% identical), Y_RNA (90% identical), Y_RNA (89% identical), RNY1P8 (88% identical), Y_RNA (88% identical), RNY1P12 (87% identical), Y_RNA (87% identical), Y_RNA (86% identical), Y_RNA (85% identical), and 101 more.